ABCE1 (ATP binding cassette subfamily E member 1)
Diseases named in the same sentence as ABCE1 in open-access papers (continued):
Sharing a sentence is not in itself a finding about the gene and the disease.
cancer (continued). "One of the suggested mechanisms of drug resistance of cancer cells is upregulation of ABCE1 due to downregulation of miR-153 in lung cancer cells." (PMID 36158686, 2022). "The oncogene ADAM Metallopeptidase Domain 9 (ADAM9) and lncRNA HULC are also modulated by miR-203 to block the invasion and migration of cancer cells via targeting ATP Binding Cassette Subfamily E Member 1 (ABCE1) factor." (PMID 36016398, 2022). "Various translation regulators such as eIF4B, ABCE1 and 4E-BP1, or ribosomal proteins, for example RPL29 or RPL9 which have been linked to malignant PCa and other cancers, were found in low abundance in VCaPER." (PMID 36348939, 2022). "Accordingly, Shichijo and co-workers provided evidence that ABCE1 mRNA is ubiquitously expressed in normal and in cancer colorectal cells, including HCT116." (PMID 34440115, 2021). "On the other hand, ABCE1 mRNA is ubiquitously expressed both in normal and in cancer colorectal cells." (PMID 34440115, 2021). "We demonstrated that mutual LCP1 and ABCE1 reduction has an additive effect on cancer cell aggressiveness in vitro and in vivo, further supporting the one miRNA-multiple targets theory." (PMID 31007850, 2019). "Recently, a growing body of evidence has indicated that ABC E1 (ABCE1), a member of the ABC family, is associated with some biological behaviors of cancer cells, such as proliferation, migration, and invasion." (PMID 30455394, 2018). "Overexpression of the most significant candidate, miR-96 or downregulation of its validated gene-target, ABCE1 reduced cancer cells 2D/3D cell movement and proliferation in vitro, and abated tumor growth and metastasis formation in vivo." (PMID 30305609, 2018). "Remarkably, overexpressing miR-96 or knocking down Abce1 expression significantly inhibited tumor growth and improved overall survival, suggesting that miR-96 regulates cancer progression by targeting Abce1." (PMID 30305609, 2018). "Notably, cancer stem cells (CSCs) exhibit increased expression of ABCE1 and consequently are more resistant to EME-induced mitochondrial dysfunction." (PMID 39315278, 2024). "Furthermore, ABCE1 overexpression limits the cytotoxic effects induced by EME, providing insights into how ABCE1 hinders the impact of drugs in cancer cells." (PMID 39315278, 2024). "It is anticipated that further research into the biological regulation of ABCE1 could validate it as a potential therapeutic target for various types of cancers." (PMID 39315278, 2024). "Targeting ABCE1 or other RQC factors in translational inhibition cancer therapy may help overcome drug resistance." (PMID 39315278, 2024). "ABCE1’s role as a stabilizer of mitochondrial function during translational stalling highlights its previously unexplored potential in mitigating mitochondrial stress in cancer cells." (PMID 39315278, 2024). "The present study revealed ABCE1’s dual effect on cancer cell fate during translational stalling." (PMID 39315278, 2024). "Remarkably, Nsp1 exhibits synthetic toxicity with the translation and RQC-related factor ATP-binding cassette subfamily E member 1, which, despite its normally positive correlation with cMyc in cancer cells, is co-opted by Nsp1 to down-regulate cMyc and inhibit tumor growth." (PMID 39161732, 2024). "In this study we investigated whether other miR-96 regulated genes can enhance ABCE1’s anti-cancer effects." (PMID 31007850, 2019). "Notably, ABCE1 has also been found involved in the development of chemotherapeutic resistance in cancer cells." (PMID 30455394, 2018). "Thus, further research is warranted to dissect the exact roles of ABCE1 in cancer cells." (PMID 39315278, 2024). "Therefore, ABCE1 is suggested as miR-153 target gene modulating drug resistance of cancer cells." (PMID 36158686, 2022).
cancer (continued). "Since cancer cells may modulate the microenvironment using intercellular communication, we evaluated stromal changes by conducting immunohistochemistry (IHC) staining of tumor tissues derived from miR-96 OE, Abce1 KD, and scrambled control cells." (PMID 30305609, 2018). "This led to reduced availability of ABCE1 in the cytosol, further disrupting the substoichiometry of RQC machinery in cancer cell cytosol." (PMID 39315278, 2024). "Notably, the expression profile of various RQC factors (e.g., ASCC3, ABCE1, ANKZF1, and VCP) is dysregulated in cancer." (PMID 38798583, 2026). "The inhibition of ABCE1, ASCC3, and VCP has been shown to impede cancer cell proliferation and viability, while inhibiting NEMF/Clbn and ZNF598 may facilitate cancer cell growth and survival." (PMID 40785597, 2025). "Harnessing the mitochondrial translocation of ABCE1 and other RQC factors could potentially open new avenues for anti-cancer therapies." (PMID 39315278, 2024). "Furthermore, the dysregulation of RQC factor expression in cancer cells, including that of ASCC3, ANKZF1, ABCE1, and VCP, highlights the intricate nature of their roles in cancer." (PMID 39315278, 2024). "For example, ASCC3, ABCE1, ANKZF1, VCP have been shown to be overexpressed in cancer cells." (PMID 36187485, 2022). "Functional studies have shown that inhibition of ABCE1, ASCC3, and VCP may inhibit cancer cell growth and survival, whereas inhibition of NEMF/Clbn and ZNF598 may have opposite effects." (PMID 36187485, 2022). "We also demonstrated that while dual ABCE1+ LCP1 downregulation did not affect cancer cell extravasation, it significantly decreased tumor growth and dissemination, and increased overall survival." (PMID 31007850, 2019). "Interestingly, dual inhibition of ABCE1 and LCP1 resulted in an additive effect on cancer cell migration, invasion, and proliferation." (PMID 31007850, 2019). "Furthermore, harnessing the mitochondrial translocation of ABCE1 and other RQC factors could potentially open new avenues for the therapeutic intervention of cancer and possibly other diseases." (PMID 39315278, 2024). "Interestingly, RQC factors can display opposing functions in cancer development and suppression depending on specific circumstances, with some factors like ABCE1, ASCC3, and VCP suppressing cancer cell growth upon downregulation, while others like NEMF/Clbn and ZNF598 may promote it upon inhibition." (PMID 38798583, 2026). "Besides the targeting of ATP Binding Cassette Subfamily E Member 1 (ABCE1) factor, involved in tumor growth, miR-203 also modulated the oncogene ADAM Metallopeptidase Domain 9 (ADAM9) and long non-coding RNA HULC to inhibit the invasion and migration of cancer cells." (PMID 34069740, 2021). "Initial omics‐based analyses have shown dysregulation in the expression of several RQC genes, such as ASCC3, ABCE1, ANKZF1, and VCP, in cancer cells; however, there is a lack of direct mechanistic studies." (PMID 40785597, 2025). "Moreover, computational prediction did not reveal gene fusions or any other physical relationship between ABCE1 and LCP1 that can explain their additive role in cancer progression (data not shown)." (PMID 31007850, 2019).
tumor (18 papers, 2012 to 2026). "In conclusion, the ABCE1 gene is not only closely associated with tumor cell migration and invasion, but is also important in promoting tumor cell proliferation." (PMID 25815591, 2015). "Analysis of fibroblast activation (αSMA staining) indicated that overexpressing miR-96 or knockdown of Abce1 in tumor cells was associated with significant reduction in activated αSMA in the tumor stroma, while collagen deposition (Sirius red staining) was not significantly altered." (PMID 30305609, 2018). "Intrigued by our in vitro results, we set out to analyze the functional roles of miR-96 and ABCE1 in tumor growth and lung metastases formation in vivo." (PMID 30305609, 2018). "Using these data, we found that miR-96 expression was inversely correlated with basal intrinsic subtype and higher tumor grade while ABCE1 expression was correlated with basal intrinsic subtype and higher tumor grade." (PMID 30305609, 2018). "We then assessed the effect of miR-96 OE and ABCE1 KD on cell migration within a native-like 3D tumor microenvironment using an extracellular matrix assay." (PMID 30305609, 2018). "The results showed that ABCE1 down-regulation significantly decreased the tumor weight after treatment with TMZ in comparison with the control group." (PMID 30455394, 2018). "We also demonstrated that miR-96 and ABCE1 play central roles in abating tumor growth and dissemination in vivo: either increasing miR-96 or decreasing ABCE1 in tumor cells was sufficient to significantly decrease tumor growth and metastasis formation." (PMID 30305609, 2018). "It has been demonstrated that inhibiting the expression of ABCE1 in tumor cells markedly inhibits tumor cell growth." (PMID 25815591, 2015). "However, there is still much work needed to comprehend how ABCE1 contributes to tumor formation and metastasis." (PMID 39315278, 2024). "However, some CRGs with CNV loss, such as IDH2, MTHFD1L, and ABCE1, showed upregulated mRNA expression, while other CRGs with CNV gain, such as TPK1, showed downregulated mRNA expression between tumor and normal samples." (PMID 36505852, 2022). "It is likely that mammals may have evolved additional roles of ABCE1 in regulating the tumor suppressor roles of RNase L by regulating RNase L enzyme activity." (PMID 33670646, 2021). "The use of shRNAs, micro-RNAs, and monoclonal antibodies that directly inhibited ABCE1, ABCC1, and ABCB5 in vivo was followed by decreased tumor growth." (PMID 39861164, 2025). "For TMZ specifically, the inhibition of ABCB1, ABCG2, ABCE1, ABCC1, and ABCB5 has seen significant decreases in either GBM tumor volume/weight by (~40–90% reduction), or significant increases in median survival (~1.3- to 5-fold increase)." (PMID 39861164, 2025). "A significantly higher expression of ABCE1 and ZNF598 was found in tumor tissues compared to adjacent normal tissues." (PMID 39315278, 2024). "After demonstrating the additive effect of LCP1 KD and ABCE1 KD in vitro, we analyzed the functional roles of dual ABCE1 and LCP1 inhibition on tumor growth, disease progression, and overall survival in vivo." (PMID 31007850, 2019). "Therefore, inhibiting the expression of ABCE1 in tumor cells may have an effect on tumor therapy." (PMID 25815591, 2015). "A total of 12 upregulated and one downregulated genes were found to overlap with prognostic and fitness genes, in which four upregulated genes (TUBA1C, ABCE1, UBE2N, and NIFK) had been reported to play roles in tumor growth, cell cycle, migration, metastasis, and prognosis." (PMID 31867042, 2019). "After reviewing the literature, we found that four upregulated genes comprising of TUBA1C, ABCE1, UBE2N, and NIFK had been reported to function in tumor growth, proliferation, migration, metastasis, and prognosis." (PMID 31867042, 2019).
tumor (continued). "Furthermore, in vivo analysis of dual ABCE1 and LCP1 knockdown resulted in significant tumor growth inhibition, decreased metastatic activity, and contributed to survival compared to either gene, separately." (PMID 31007850, 2019). "The ABCE1 gene is located on autosomal 4q3l and a member of the APT binding cassette transporter subfamily, which is highly conserved, codes ribonuclease L protein and is involved in tumor growth and development." (PMID 25815591, 2015).
infection (6 papers, 2012 to 2024). The state of being infected such as from the introduction of a foreign agent such as serum, vaccine, antigenic substance or organism. "In contrast, genes such as Abce1 and Ptpn11 were only upregulated following rpoB-H445Y Mtb infection, whereas Uba7 was upregulated only during wt Mtb infection." (PMID 38603763, 2024). "The increase in LC3-II conversion and P62 degradation continued at 8 h post infection in ABCE1 KD cells." (PMID 33670646, 2021). "Compared to WT cells, increased conversion of LC3-I to LC3-II was observed in ABCE1 KD cells that correlated with the degradation of the autophagy receptor, P62, as early as 4 h post infection." (PMID 33670646, 2021). "The initial characterization of ABCE1 supported an inhibition of antiviral role of IFN during infection with EMCV and HIV." (PMID 33670646, 2021). "There was a gradual increase in mRNA levels as the infection spread to new cells, which was less pronounced in ABCE1 siRNA-treated cells, resulting in statistically significant differences starting at 48 h after infection." (PMID 31088929, 2019). "However, treatment with both autophagy inhibitors reduced EMCV titers more drastically in ABCE1 KD cells at both 4 h and 8 h post infection compared to WT cells." (PMID 33670646, 2021). "The ABCE1 proviral effect requires viral gene expression in the context of infection." (PMID 31088929, 2019). "As expected, ABCE1 expression was significantly repressed after infection." (PMID 22267055, 2012). "N protein mRNA levels remained stable for the first 12 h after infection and then increased around 100-fold within the next 12 h irrespective of ABCE1 levels, reflecting the first round of replication." (PMID 31088929, 2019). "Additionally, an ATP-binding protein termed ABCE1 was shown to regulate the activity of RNase L. ABCE1 inhibits the antiviral activity of RNase L against EMCV and was reported to be essential for infection by viruses that are naturally UpA rich." (PMID 33402534, 2021).
ABCE1 also shares sentences with these, for which no sentence is quoted: acute pancreatitis (1 paper); breast tumor (1); neuroblastoma (1); oesophageal cancer (1); oral squamous cell carcinoma (1); ovarian carcinoma (1); renal cell cancer (1); Sepsis (1).